AARS2 (alanyl-tRNA synthetase 2, mitochondrial)
Diseases named in the same sentence as AARS2 in open-access papers (continued):
Sharing a sentence is not in itself a finding about the gene and the disease.
colorectal cancer (2 papers, 2022 to 2025). A primary or metastatic malignant neoplasm that affects the colon or rectum. "Mechanistically, CAF‐derived EV‐packaged circTAX1BP1 is delivered to colorectal cancer (CRC) cells, where it binds to VIRMA and promotes its lactylation at lysine residue 1713 by recruiting AARS2." (PMID 41017455, 2025). "AARS2 and FOXO3 are protective factors in the prognostic model of CRC, and the former regulates the proliferation of colorectal cancer by affecting mitochondrial respiration." (PMID 36299603, 2022).
Encephalopathy (2 papers, 2014 to 2019). Encephalopathy is a term that means brain disease, damage, or malfunction. "The combination of encephalopathy and myopathy strongly suggest that AARS2‐related leukoencephalopathy is a new variant of mitochondrial encephalomyopathy." (PMID 30706699, 2019). "Nevertheless, encephalopathy is the most common presentation in aaRS2 mutations, as in several other OXPHOS disorders, probably because of the high energy request by the central nervous system." (PMID 24827421, 2014).
gastric cancer (2 papers, 2025 to 2026). A primary or metastatic malignant neoplasm involving the stomach. "In gastric cancer cells, elevated copper levels promote lactylation of METTL16 at the K229 site, mediated by enhanced interaction with acetyltransferases alanyl-tRNA synthetase 1/2 (AARS1/AARS2)." (PMID 41459114, 2026). "In gastric cancer, increased copper level improves AARS1/AARS2-METTL16 interaction." (PMID 40994548, 2025). "The balance between AARS1/AARS2’s lactylation and alanine transfer functions involves competitive inhibition: alanine inhibits AARS’s lactylation activity, with β-alanine pretreatment dramatically reducing the lactylation levels in gastric cancer cells." (PMID 40994548, 2025).
hepatocellular carcinoma (2 papers, 2023 to 2025). A malignant tumor that arises from hepatocytes. "An elevated expression of AARS2 has been highlighted among most cancers, especially colorectal cancer (CRC), hepatocellular carcinoma (HCC), and COAD, and it is closely associated with poor prognosis and survival in HCC and COAD patients." (PMID 41008630, 2025). "The molecular characterization of AARS2 was confirmed in hepatocellular carcinoma (HCC) using proteomics analysis, quantitative real‐time PCR, western blotting, immunohistochemical staining, and cell experiments." (PMID 37990642, 2023).
infantile hypertrophic cardiomyopathy (2 papers, 2014 to 2025). "Recently autosomal recessive mutations were reported in the AARS2 and MTO1 genes in patients with infantile hypertrophic cardiomyopathy." (PMID 24412566, 2014).
colon cancer (1 paper, 2023). "Recently, an oncology study has proposed that AARS2 could serve as a prognostic indicator for predicting survival in colon cancer." (PMID 37990642, 2023).
Combined oxidative phosphorylation deficiency type 8 (1 paper, 2025). "Combined oxidative phosphorylation deficiency type 8 (COXPD8) is an autosomal recessive disorder caused by a mutation of a mitochondrial alanyl-tRNA synthetase gene (AARS2) encoded on chromosome 6." (PMID 40863384, 2025). "Combined oxidative phosphorylation deficiency type 8 (COXPD8) is an autosomal recessive mitochondrial disorder caused by a mutation of the nuclear encoded mitochondrial alanyl-tRNA synthetase gene (AARS2)." (PMID 40863384, 2025).
developmental delay (1 paper, 2025). "In this article, the authors report a case of a novel homozygous mutation in the AARS2 gene in a 17-month-old Middle Eastern girl presenting with global developmental delay, hypotonia, and who has been followed up until she is now 10 years old and has started to develop dystonia as well." (PMID 40688999, 2025).
fibrosis (1 paper, 2025). the formation of excess fibrous connective tissue in an organ or tissue in a reparative or reactive process. "Wheat germ agglutinin (WGA) staining showed that cardiomyocyte hypertrophy was evident in Aars2 cKO hearts, and Masson staining indicated severe cardiac fibrosis in Aars2 cKO hearts compared with Aars2fl/fl hearts at 28 d after induction." (PMID 40371904, 2025).
leukoencephalopathy, progressive, with ovarian failure (1 paper, 2022). "AARS2 mutations cause a recessive form of ALSP now named leukoencephalopathy, progressive with ovarian failure (LKENP)." (PMID 35683020, 2022).
mitochondrial encephalomyopathy (1 paper, 2019). A heterogenous group of disorders characterized by alterations of mitochondrial metabolism that result in muscle and nervous system dysfunction. "Here, we report the first description of typical ragged red fiber (RRF) identified by muscle biopsy in a male patient with AARS2‐related leukoencephalopathy, suggesting that AARS2‐related leukoencephalopathy be a new variant of mitochondrial encephalomyopathy." (PMID 30706699, 2019).
mitral valve prolapse (1 paper, 2024). A fairly common and often benign valvular heart disorder characterized by redundancy or hooding of mitral valve leaflets so that they prolapse into the left atrium, often causing mitral regurgitation. "Heart phenotype in patients with NARS2 deficiency was rare with mitral valve prolapse and cardiac dysfunction, while myocardial dysfunction has been reported in other aaRSs, including AARS2 and Lysyl-tRNA synthetase (KARS)." (PMID 38310242, 2024).
Myocardial fibrosis (1 paper, 2025). "By applying intraperitoneal injection of tamoxifen to induce Cre-LoxP mediated cardiac specific deletion of Aars2 for 5 d, we measured cardiac function by echocardiography (ECHO) at various time points and myocardial fibrosis by Masson staining at the experimental endpoint." (PMID 40371904, 2025).
myocardial infarction (1 paper, 2025). Gross necrosis of the myocardium, as a result of interruption of the blood supply to the area, as in coronary thrombosis. "(A, B) Western blot and quantitative real-time PCR (qRT-PCR) analysis showing reduced expression of AARS2 proteins (A) or mRNA (B) of 3 d myocardial infarction (MI) hearts compared with sham hearts (n=3)." (PMID 40371904, 2025). "Cardiomyocyte-specific AARS2 overexpression in mice improved cardiac function and reduced cardiac fibrosis after myocardial infarction (MI), without affecting cardiomyocyte proliferation and coronary angiogenesis." (PMID 40371904, 2025).
Perrault syndrome (1 paper, 2025). Perrault syndrome (PS) is characterized by the association of ovarian dysgenesis in females with sensorineural hearing impairment. "Men with Perrault syndrome caused by PMD gene variants, or with AARS2 variants, have not been reported to have oligospermia or azoospermia." (PMID 39891580, 2025).
pneumonia (1 paper, 2025). An acute, acute and chronic, or chronic inflammation focally or diffusely affecting the lung parenchyma, caused by an infection in one or both of the lungs (by bacteria, viruses, fungi, or mycoplasma.). "In experimental models of pneumonia, Fbxo24-deficient mice show elevated AARS2 levels accompanied by enhanced pulmonary immune cell infiltration and cytokine production, indicating that AARS2 accumulation amplifies host immune responses." (PMID 41357216, 2025).
Premature ovarian insufficiency (1 paper, 2025). Amenorrhea due to loss of ovarian function before the age of 40. "Herein, we report that elevated lactate and gain-of-function mitochondrial AARS (AARS2) mutations-induced hyper-lactylation promotes premature ovarian insufficiency (POI)." (PMID 40301335, 2025).
mitochondrial disease (8 papers, 2014 to 2025). "AARS2 gene mutations result in a mitochondrial disease with variable clinical manifestations dependent on the exact mutation." (PMID 40688999, 2025). "Overall, our data strengthen the importance of mt-AlaRS in cardiac muscle during early embryonic development and the relationship between β-barrel subdomain variants (p.Arg580Trp and p.Arg592Trp) and the manifesting AARS2-related mitochondrial disease phenotypes." (PMID 30285085, 2019). "AARS2 intragenic deletions affecting the same exons as P2 have been previously identified through ES and GS in two unrelated patients with AARS2-related mitochondrial disease." (PMID 33924034, 2021). "In conclusion, we identified novel mutations in two genes encoding mitochondrial aminoacyl-tRNA synthetases (VARS2 and TARS2), which have not been appreciated previously as causing mitochondrial disease, thus expanding the list of aaRS2-associated diseases." (PMID 24827421, 2014).
cancer (6 papers, 2023 to 2026). A tumor composed of atypical neoplastic, often pleomorphic cells that invade other tissues. "The abnormal expression of AARS2 was prominently associated with activity of cancer pathways and performed oncogenic roles in most cancers." (PMID 37990642, 2023). "Subsequently, the genomic landscape of AARS2 was depicted in 33 human cancer types, including mutations, CNA, and gene methylation." (PMID 37990642, 2023). "Meanwhile, similar findings were also elaborated that AARS2 expression is positively associated with CNA in most cancers, including CHOL and LIHC." (PMID 37990642, 2023). "AARS2 was tightly associated with multiple oncogenic pathways across most of cancers." (PMID 37990642, 2023). "Notably, the CNA of AARS2 occurred significant gain and loss in multiple cancers, such as KICH, SKCM, and UVM." (PMID 37990642, 2023). "The copy number alteration (CNA) might be key driver to causing aberrant expression of AARS2 in many cancers." (PMID 37990642, 2023). "In summary, this review highlights the novel lactylation-dependent roles of AARS1 and AARS2 in cancers that extend beyond their canonical functions in protein synthesis." (PMID 41008630, 2025). "AARS1 and AARS2 are generally upregulated in many cancers, consistent with increased protein synthesis demand." (PMID 41008630, 2025). "AARS2 is frequently amplified across multiple cancers, including lung adenocarcinoma, lung squamous cell carcinomas, and breast invasive carcinoma, suggesting its potential pro-tumorigenic role." (PMID 41008630, 2025). "Similar findings were also observed that AARS2 displayed tight correlation with immune checkpoints in some cancers, such as DLBC, GBM, and SKCM." (PMID 37990642, 2023). "In this study, the AARS2 gene was broadly investigated regarding genomic alterations, biological function, prognosis, and therapeutic implications across 33 human cancer types." (PMID 37990642, 2023). "The AARS2 was revealed to be a novel and promising biomarker for prognosis and immunotherapy responses in human cancers." (PMID 37990642, 2023). "As only partial methylation sites harbored significant correlation, CNA of AARS2 was further investigated across pan‐cancer." (PMID 37990642, 2023). "From the perspective of AARS2 expression, our study made efforts on identifying potential drugs and targeted pathway for cancers." (PMID 37990642, 2023). "The ARSs have been reported harboring crucial role in human cancer, while AARS2 as one of them remains almost a blank space in human cancer." (PMID 37990642, 2023). "Our investigation has encompassed genomic alterations, biological functions, prognostic implications, and the therapeutic potential of AARS2 in various human cancers." (PMID 37990642, 2023). "The comprehensive investigations increased the understanding of AARS2 across human cancers and generated beginning insights of AARS2 in genomic landscape, molecular biological function, prognosis, and clinical treatment." (PMID 37990642, 2023). "There is a pressing need to enhance our in‐depth and comprehensive understanding of AARS2, both in terms of molecular characterization and its potential clinical implications across a wide spectrum of human cancers." (PMID 37990642, 2023). "The AARS2 displayed consensus biological activity and was widely involved in proliferation‐related activity across almost of all cancers." (PMID 37990642, 2023). "As one member of the ARS family, the mitochondrial alanyl‐tRNA synthetase 2 (AARS2) is coding by nuclear genome and performing function in chondriosome, which remains largely unexplored in human cancers." (PMID 37990642, 2023). "Based on gene expression level, AARS2 displayed frequently elevated mRNA expression across most cancers, especially in HCC types." (PMID 37990642, 2023).
cancer (continued). "Targeting the regulatory mechanisms controlling the oncogenic functions of AARS1 and AARS2, particularly lactylation-related mechanisms, holds promising therapeutic potential for cancers but requires confronting challenges by developing isoform-specific and function-specific inhibitors." (PMID 41008630, 2025). "Interestingly, AARS2 also appeared poised to carry out diverse functional roles in different cancers." (PMID 37990642, 2023). "In addition, AARS2 also displayed the consensus and same biological activity across almost all cancers, which harbored conspicuous positive relationship with proliferation‐related pathways such as G2M checkpoint, Wnt/β‐catenin pathway, and MYC Targets V2." (PMID 37990642, 2023). "All these novel findings indicated that AARS2 might be a promising biomarker for predicting prognosis and immunotherapy responses in cancer." (PMID 37990642, 2023). "Furthermore, GO and KEGG enrichment analyses suggested that AARS2 was closely links with cell cycle, mTOR signaling pathway, and cancer metabolism activity." (PMID 37990642, 2023). "However, AARS2 was negatively related to immune‐inflammatory pathways in other cancers." (PMID 37990642, 2023). "Interestingly, AARS2 was likely to perform multiple functional roles in different cancers." (PMID 37990642, 2023). "This CDH1‐VHL‐HIF1α/AARS2‐R5P/TKTL1 circuit is supported by the observation that low R5P levels and high CDH1 expression correlate with proliferating cancer cells and tissues." (PMID 41020695, 2025). "It is of significance to identify the tissue- or cancer-specific functions of AARS1 and AARS2, extending beyond their canonical roles in protein synthesis, particularly concerning the novel regulatory mechanism of lactylation." (PMID 41008630, 2025). "Apoptosis (e.g., BID, CASP6, etc.)and aminoacyl-tRNA biosynthesis (e.g., CARS2 and AARS2) were predominant in the D4 (HGIN stage), suggesting cancer malignancy." (PMID 36991000, 2023). "According to the correlation between AARS2 expression and the IC50 value of drugs, novel insights were proposed for cancer drug therapy." (PMID 37990642, 2023). "In this study, we discovered a novel tumor‐promotive factor AARS2 in HCC and decoded its molecular characterization in 33 human cancer types." (PMID 37990642, 2023). "According to estimating the relationship between AARS2 and tumor biological activity and clinical transformation, the AARS2 performed as an oncogenic gene in HCC and could be a promising biomarker for prognosis and immunotherapy in human cancers." (PMID 37990642, 2023). "Overall, the AARS2 was an oncogenic gene in HCC and might perform a similar role in most cancers." (PMID 37990642, 2023).
myopathy (4 papers, 2014 to 2023). A disease of the muscle in which the muscle fibers do not function properly. "P6 was a 9-year-old male with seizures, myopathy and ophthalmological findings whose findings started at the postnatal third month and carried a compound heterozygous variant in the AARS2 gene." (PMID 37377599, 2023). "Seven patients with infantile-onset cardiomyopathy and AARS2 mutations have been reported and one who died in utero was described to have myopathy, hypotonia and multiple fractures." (PMID 25705216, 2015).
tumor (3 papers, 2023 to 2026). "Subsequent multi-faceted oncogenic characterization of AARS2 encompassed its expression profiles, diagnostic and prognostic value, and associations with tumor microenvironment heterogeneity." (PMID 41836446, 2026). "In addition, only one tumor‐associated research declares that AARS2 is a protective indicator in colorectal cancer and regulates cell proliferation via interfering mitochondrial respiration." (PMID 37990642, 2023). "Immunohistochemical validation in clinical COAD specimens confirmed higher AARS2 protein levels in tumor tissues versus adjacent normal mucosa; concurrent elevation of cGAS protein was observed, though functional activity requires contextual interpretation." (PMID 41836446, 2026). "Three indicators—IHC positive area, IHC area density, and H‐Score—all supported AARS2 expression dramatically increased in 64 paired tumor tissues." (PMID 37990642, 2023). "Consistent with proteomic conclusion, WB analysis proved AARS2 had pronouncedly high expression again in HCC tumor samples." (PMID 37990642, 2023). "Using tumor cell information, a novel insight was decoded that AARS2 expression presented a positive correlation with CNA." (PMID 37990642, 2023). "Taken together, AARS2 might serve as a novel oncogenic gene and perform a tumor‐accelerative role in HCC." (PMID 37990642, 2023).
metabolic disease (2 papers, 2019 to 2025). A congenital disorder (due to inherited enzyme abnormality) or acquired (due to failure of a metabolically important organ) disorder resulting from an abnormal metabolic process. "Notably, movement disorders are often associated with metabolic diseases and have been described in conditions related to deficiencies in other aminoacyl-tRNA synthetases, including WARS2, CARS2, PARS2, RARS2, and AARS2." (PMID 41002930, 2025).
genetic diseases (1 paper, 2019). "The white matter disease spectrum is associated with many genetic diseases, including AARS2, CADASIL, ALD, and others." (PMID 31920941, 2019).
heart disease (1 paper, 2021). "In CMs, we found three genes in OMIM (Online Mendelian Inheritance in Man) with gene × treatment interactions that are known to cause Mendelian forms of heart disease: PSMA6, AARS2, DSC2." (PMID 33988505, 2021).
neurodegenerative disease (1 paper, 2020). A disorder of the central nervous system characterized by gradual and progressive loss of neural tissue and neurologic function. "AARS2‐related ALSP is an autosomal recessive neurodegenerative disease while CSF1R‐related ALSP is inherited in a dominant manner." (PMID 31885218, 2020).
neurological diseases (1 paper, 2021). "Given that AARS2 is responsible for the translation of mitochondrial proteins and that mitochondria dysfunction is essential in the pathogenesis of neurological diseases such as AD, it is possible that both CSF1R and AARS2 deficiency affects the mitochondrial structural and functional integrity." (PMID 34867307, 2021).
AARS2 also shares sentences with these, for which no sentence is quoted: dementia (4 papers); cognitive decline (3); hypertrophic cardiomyopathy (3); epilepsy (2); optic atrophy (2); adrenoleukodystrophy (1); Bell's palsy (1); brain disease (1); cerebellar ataxia (1); Cerebellar atrophy (1); cerebral arteriopathy with subcortical infarcts and leukoencephalopathy (1); cervical cancer (1); cognitive defects (1); colon adenocarcinoma (1); colorectal tumor (1); deafness (1); Dystonia (1); endocrine diseases (1); Fabry disease (1); galactosemia (1); Globoid cell leukodystrophy (1); Gordon Holmes syndrome (1); heart failure (1); hypogonadism (1); Intellectual disability (1); intellectual disability syndrome (1); Leigh syndrome (1); liver failure (1); metachromatic leukodystrophy (1); movement disorder (1).
A further 12 diseases each share a sentence with AARS2 in 1 paper.